TLR4 (toll like receptor 4)
Diseases named in the same sentence as TLR4 in open-access papers (continued):
Sharing a sentence is not in itself a finding about the gene and the disease.
renal fibrosis (continued). "We hypothesized that relaxin induces M2 macrophage polarization by inhibiting the TLR4-NF-κB signaling pathway and alleviates the inflammation and renal fibrosis at the early stages of UUO." (PMID 28416741, 2017). "Therefore, we demonstrated for the first time that H2 relaxin can shift macrophage polarization toward the M2 phenotype by downregulating the TLR4-NF-ΚB signaling pathway, thus alleviating renal fibrosis." (PMID 28416741, 2017). "HMGB1, the ligand of TLR4, can promote renal fibrosis by facilitating the M1 macrophage phenotype." (PMID 28416741, 2017). "In summary, TLR4 contributes to renal fibrosis and CKD progression, at least in part, via inflammasome activation in renal epithelial cells, and may also participate in the dysregulated immune response that is associated with CKD." (PMID 26416975, 2015). "In the kidney, renal fibrosis induced by urethral obstruction is promoted by TLR4 activation." (PMID 23585870, 2013). "We demonstrated evidence that loss of Chop represses Hmgb1/TLR4 signaling following UUO induction, leading to repressed NFκB transcriptional activity along with suppressed IL-1β production, which then reduces TGF-β1 production and Pi3K/Akt activity to attenuate the development of renal fibrosis." (PMID 26247732, 2015). "Interestingly, it seems that TLR4 was probably the primary receptor for Hmgb1 in our model of UUO-induced renal fibrosis as Chop deficiency did not affect UUO-induced expression of TLR2 and RAGE but attenuated TLR4 by twofold." (PMID 26247732, 2015). "Impaired TRIF rather than MyD88 signaling might account for less renal fibrosis in Tlr4-deficient mice." (PMID 21544241, 2011). "Oleanolic acid improves energy metabolism mainly through the AMPK/PGC-1α pathway and inhibits TLR4/NF-κB inflammatory signaling, reducing TGF-β1 and collagen deposition in renal tissues, thereby alleviating renal fibrosis and inflammatory response." (PMID 41019991, 2025). "AS-IV has the potential to impede the progression of renal fibrosis by mitigating the TGF-β1/Smad and TLR4/NF-κB signaling pathways, thereby preventing fibrosis." (PMID 39652245, 2024). "Sal significantly inhibited the expression of TLR4, p38, ERK and JNK in the mouse model and improved renal fibrosis." (PMID 37565908, 2023). "Aa for 2) Diabetic nephropaty, BAE rescued renal fibrosis via modulating AngII, TGF–β, α-SMA protein expression as well as p38MAPK/NF-κB transduction while WGS and WGI both negatively-regulated TLR4/NF-κB to protect renal tissue." (PMID 36188625, 2022). "Low molecular weight hyaluronan fragments appear to be implicated in the inflammatory cascade through activation of toll-like receptor-4 (TLR4) and -2 (TLR2) as well as in the genesis of renal fibrosis." (PMID 33671524, 2021). "MSCs transfusion effectively suppressed renal fibrosis in experimental models by inhibiting both the pro-inflammatory and pro-fibrotic signaling pathways, including TGF-β1/Smad3, TLR4/NK-κB, and ERK." (PMID 32512831, 2020). "The increases of serum BUN, Scr, renal fibrosis-related genes and proteins (Vimentin, α-SMA, and TGF-β1), and autophagy-related genes and proteins, (ATG5 and LC3II) were inhibited in TLR4−/− mice." (PMID 32108135, 2020). "Because of the tight link between TLRs and inflammatory diseases, TLR4 is extensively involved in renal fibrosis and chronic kidney disease progression and the expression of TLR2 and TLR4 mediates ischemia/reperfusion injury." (PMID 31011483, 2019). "The present study shows that Sal obviously suppresses the expression of TLR4, p-IкBα, p-NF-κB, p-Ρ38, p-ERK, and p-JNK, relieving the inflammatory response and ameliorating renal fibrosis." (PMID 30836660, 2019). "Further researches have reported that TLR4 knockout diabetic mice have reduced the expression of MyD88 and TRIF and decreased NF-κB activity and the release of inflammatory cytokines and renal fibrosis." (PMID 29861832, 2018).
renal fibrosis (continued). "Accordingly, evidence for renal colonization by leptospira inducing a mild renal fibrosis in mice through TLR- and NLR-independent pathways would explain the TLR4-independent effect of GLP." (PMID 25265888, 2014). "Additionally, it markedly reduces the release of inflammatory cytokines and hinders the TLR4/NF-κB and MAPK signaling pathways, indicating Salidroside’s potential as a promising therapeutic approach for renal fibrosis." (PMID 39652245, 2024). "Recent research found that less secretion of C3 appears to inhibit the activation of the High-Mobility Group Box 1 (HMGB1)-TLR4-p65 pathway signal pathway and the production of transforming growth factor-β (TGF-β1), thereby alleviating renal fibrosis in unilateral ureteral obstruction (UUO) mice." (PMID 36973754, 2023). "Finally, the BYF regulatory mechanism on renal fibrosis and inflammation was validated in vitro with TGF-β1-induced HK2 cells and TLR4 siRNA." (PMID 34867380, 2021). "In addition, the proteinuria, renal insufficiency, inflammation, and renal fibrosis of STZ-induced diabetic mice with TLR4 knockout were protected, and TLR4 inhibition prevented renal tubular damage and reduced the loss of podocytes in DKD." (PMID 33692782, 2021). "Astragaloside IV may potentially protect against renal fibrosis by reducing oxidative stress and inflammation via transforming growth factor-β1 (TGF-β1)/Smads signaling or the toll-like receptor 4 (TLR4)/nuclear factor kappa-B (NF-κB) signaling pathway." (PMID 33854427, 2020). "Tripterygium glycoside and triptolide could alleviate renal fibrosis involving the miR-141-3p/phosphatase and tensin homolog/AKT/mTOR pathway, TGF-β1/Smad3 pathway and TLR4/NF-κB pathway." (PMID 33854427, 2020). "The results indicated that the renal fibrosis induced by OTA and CsA could be related to TLR4 and autophagy." (PMID 32108135, 2020). "Moreover, Sal ameliorates renal fibrosis by reducing ECM accumulation and blocking the TLR4/NF-кB and MAPK signaling pathways." (PMID 30836660, 2019). "TLR4 expression is significantly increased after UUO and induces renal fibrosis." (PMID 28416741, 2017). "Extracellular Hmgb1 thus bound to TLR4, and by which, it activated MyD88-NFκB pathway to enhance IL-1β expression, which in turn promoted TGF-β/Smad2/3 and Pi3k/Akt signaling to exacerbate renal fibrosis." (PMID 26247732, 2015). "Since LPS may modulate TGF-β synthesis in pericytes, we speculated that LPS/TLR4 signaling contributes to further accumulation of TGF-β, amplifying LPS signaling and developing a self-sustaining positive feedback loop that initiates collagen accumulation and leads to renal fibrosis progression." (PMID 31357597, 2019).
osteoarthritis (77 papers, 2008 to 2025). A noninflammatory degenerative joint disease occurring chiefly in older persons, characterized by degeneration of the articular cartilage, hypertrophy of bone at the margins and changes in the synovial membrane. "TLR4 has been previously implicated in the pro-inflammatory response of chondrocytes to high fluid shear, and increasing evidence highlights a role of TLR4 activation in inflammatory and catabolic processes associated with osteoarthritis pathogenesis." (PMID 30891042, 2019). "Numerous studies on the TLR4-dependent mechanisms of arthritic diseases such as RA and osteoarthritis have been conducted to identify the mechanisms underlying the inflammation response observed during these diseases and thereby to facilitate the discovery of new therapeutic agents." (PMID 31028244, 2019). "RESATORVID, functioning as a TLR4 inhibitor, exhibits the capacity to ameliorate osteoarthritis pathology by impeding chondrocyte pyroptosis and degeneration." (PMID 40657379, 2025). "In monosodium iodoacetate (MIA)-induced osteoarthritis rat model, curcumin possessed an anti-inflammatory effect against osteoarthritis and prevented knee damage via blocking the TLR4/NF-κB signaling pathway." (PMID 40437595, 2025). "6-shogaol has been shown to prevent cartilage damage and synovial inflammation in osteoarthritis by hindering the interaction between TLR4/MD-2 complex in chondrocytes." (PMID 39976020, 2025). "In terms of osteoarthritis, naringenin was reported to attenuate inflammation and apoptosis of osteoarthritic chondrocytes via the TLR4/TRAF6/NF-κB pathway." (PMID 40027098, 2025). "Osteoarthritis (OA), where TLR4/MD2 signaling in chondrocytes and synoviocytes plays a role in cartilage degradation and inflammation." (PMID 39976020, 2025). "It was subsequently demonstrated that exosome-mediated PVT1 targets miR-93-5p, modulates the activity of the HMGB1/TLR4/NF-κB pathway, and influences the progression of lipopolysaccharide-induced osteoarthritis." (PMID 40636390, 2025). "The results revealed that naringenin alleviated the pathological symptoms of osteoarthritis in mice, reduced the expression of TLR4 and TRAF6, and the phosphorylation of NF-κB in knee cartilage tissue." (PMID 37953787, 2023). "The TLR family, especially TLR4, plays a vital role in the initiation of DCs in osteoarthritis, which expedites the progression of osteoarthritis." (PMID 37388748, 2023). "MiR-93 inhibits chondrocyte apoptosis in osteoarthritis by targeting the TLR4/NF-κB signaling pathway." (PMID 36983002, 2023). "Previous studies had demonstrated that astilbin ameliorates osteoarthritis by suppressing TLR4/MD-2 and NF-κB signaling." (PMID 36824696, 2023). "LINC01385 downregulation abolished progression of osteoarthritis via sponging miR-140–3p and increasing TLR4 expression." (PMID 37779916, 2023). "Suppression of lncRNA SNHG14 blocked FSTL-1-induced NLRP3 and TLR4/NF-kappaB pathways via regulation of miR-214–3p, conferring to inhibition of osteoarthritis." (PMID 37779916, 2023). "A previous study showed miR-6891-3p targeting TLR4, thereby inhibiting inflammatory response in osteoarthritis." (PMID 37996941, 2023). "LncRNA IGHCγ1 reduced the expression of miR-6891–3p and upregulated TLR4 expression levels, contributing to regulation of macrophage inflammation in osteoarthritis." (PMID 37779916, 2023). "Age-related variations in TLR4 expression have been identified, with functional implications in managing conditions like emphysema, osteoarthritis, and cardiovascular resilience." (PMID 38001481, 2023). "Compared with healthy people or osteoarthritis (OA) patients, TLR4 is increased significantly, while the degradation of TLR4 has been found to alleviate symptoms of RA in mouse models." (PMID 37252680, 2023). "TLRs are expressed in articular cartilage and synovial fibroblasts of patients with osteoarthritis; TLR4 is the primary receptor form of TLRs in chondrocytes." (PMID 37953787, 2023).
osteoarthritis (continued). "For example, Meng et al21 reported that overexpression of PVT1 aggravates the LPS-induced osteoarthritis inflammation by regulating the HMGB1/TLR4 axis and NF-κB pathway." (PMID 35723715, 2022). "TLR4 is involved in the production of innate immune factors that increase synovitis, cartilage degradation and osteoarthritis." (PMID 35865531, 2022). "A previous study demonstrated that miR‐93 inhibited chondrocyte apoptosis and inflammation in osteoarthritis by targeting TLR4/nuclear factor‐κB signaling pathway." (PMID 34076365, 2021). "For instance, lncRNA IGHCγ1 served as a ceRNA to modulate macrophage inflammation in osteoarthritis by targeting miR-6891-3p and modulating TLR4 expression." (PMID 34672863, 2021). "So MIAT knockdown alleviates LPS-induced chondrocytes inflammatory injury via regulating miR-488-3p/SOX11 axis through NF-κB signaling pathway and regulating TLR4 expression in osteoarthritis." (PMID 34124371, 2021). "The low‐grade, chronic inflammation initiated by TLR4‐triggered innate immune responses has a central role on early osteoarthritis." (PMID 31876072, 2020). "Because inflammation in osteoarthritis (OA) is related to the Toll-like receptor 4 (TLR4) signaling cascades, TLR4 is a reasonable target for developing therapeutics for OA." (PMID 33060735, 2020). "Amurensin H is a resveratrol dimer with anti‐inflammatory and anti‐apoptotic effects, while its effects on TLR‐4 signals to inhibit osteoarthritis are still unclear." (PMID 31876072, 2020). "Our results demonstrate that the signaling through TLR-4 is a proinflammatory mechanism in osteoarthritis that drives the upregulation of MMP-3, IL-1β, and TNF-α gene expression, leading to cartilage degradation and inflammation." (PMID 23118784, 2012). "Expression of TLR2 and TLR4 has been shown to be increased in the synovial tissue of RA patients compared with healthy donors or osteoarthritis samples." (PMID 20419126, 2010). "In another study, CA applied at doses of 20 and 50 μmol/L was shown to inhibit the expression of IL-1β, IL-6 and TNF-α and the activation of the toll-like receptor 4/myeloid differentiation primary response 88 (TLR4/MyD88) signaling pathway in LPS-induced osteoarthritis fibroblast-like synoviocytes." (PMID 40722869, 2025). "Additionally, their derived exosomes have been shown to inhibit inflammation in osteoarthritis through the HMGB1/TLR4/NF-κB pathway, a promising avenue for therapeutic intervention in KOA." (PMID 40636390, 2025). "In contrast, miR-146a modulates the TLR4/IL-1 receptor-associated kinase 1/TNF receptor-associated factor 6 signaling axis and nuclear NF-κB-mediated inflammation, thereby linking it directly to cartilage degradation and osteoarthritis progression." (PMID 41403440, 2025). "Furthermore, it has been demonstrated that the LPS-Toll-like receptor 4 (TLR4) axis contributes to the severity of osteoporosis and osteoarthritis." (PMID 38560225, 2024). "Consequently, FTO overexpression suppressed synovial inflammation and alleviated osteoarthritis by inhibiting the miR-515-5p/TLR4/MyD88/NF-κB axis in an m6A-dependent manner." (PMID 39686999, 2024). "Similarly, other DAMPs were shown to propel inflammation through the activation of TLR4 in rheumatoid and osteoarthritis, which highlights the inhibition of TLR4-mediated signaling as a potential therapeutic option." (PMID 36678520, 2022). "This study was conducted to identify whether the TLR4/MyD88/NF-κB signalling pathway plays a vital role in osteoarthritis (OA) treatment with Duhuo Jisheng Decoction (DHJSD) on the basis of a network pharmacology approach (NPA)-integrated experiment." (PMID 35140604, 2021). "Amurensin H has in vivo and in vitro anti‐inflammatory and chondroprotective effects and inhibits TLR4/Syk/NF‐κB signalling in chondrocytes, suggesting that amurensin H could be a potential candidate for disease‐modifying osteoarthritis drugs." (PMID 31876072, 2020).
osteoarthritis (continued). "Systemic or local A-SAA expression inside OA joint cavity may play a key role in inflammatory process seen in osteoarthritis, which could be counteracted by TLR4 inhibition." (PMID 23776697, 2013). "However, a potential role of TLR4 in dogs with osteoarthritis and chronic enteropathies was proven." (PMID 23016675, 2012). "For obesity-related osteoarthritis, diet rich in SFA, MUFA, and n-6 PUFA can activate the TLR4/NF-κB signaling pathway in articular cartilage, which in turn upregulates the NLRP3 inflammasome, thereby inducing pyroptosis." (PMID 37215994, 2023). "Downregulating TLR4 through PUM1 can help reduce cellular aging and osteoarthritis, indicating its potential therapeutic implications for age-related diseases." (PMID 37240754, 2023). "We have described the expression of TLR2 and TLR4 in RA FLS which exhibited increased levels of TLR4 transcripts and protein compared with FLS from osteoarthritis (OA) patients." (PMID 30155495, 2018). "Conversely and for reasons that are not yet completely understood, pharmacological antagonism of the proinflammatory transmembrane protein Toll-like receptor 4 (TLR-4) results in heightened MMP-13 expression and a corresponding dramatic increase in the severity of osteoarthritis." (PMID 27478294, 2016). "We aimed to assess effects of TLR2 and TLR4 stimulation on proinflammatory cytokine production by peripheral blood mononuclear cells (PBMCs) from patients with recent-onset RA, osteoarthrosis (OA), and healthy control (HC).Methods." (PMID 18584044, 2008). "Furthermore, the inhibition of TLR4/NF-κB activity by PUM1 improved the chondrogenic potential of MSCs and provided protection against inflammation-mediated disruption of chondrogenic formation in osteoarthritis mouse models." (PMID 38001481, 2023).